TTN (titin)
Diseases named in the same sentence as TTN in open-access papers (continued):
Sharing a sentence is not in itself a finding about the gene and the disease.
metastatic tumors (1 paper, 2021). "There were three genes (PIK3CA, USH2A, and TTN) containing neoantigens in the recurrent/metastatic tumors." (PMID 33796222, 2021). "In the recurrent/metastatic tumors, patients with neoantigens in TTN, PIK3CA, and USH2A increased CD3+ CD8+ infiltration approximately 3-fold compared to patients without neoantigens in these genes." (PMID 33796222, 2021).
mitral atresia (1 paper, 2025). "Patients in Group 2, the mitral atresia group, carried variants in the genes including EP300, NOTCH1, and TTN (mitral atresia), CREBBP, EP300, and NOTCH1 (hypoplastic left ventricle)." (PMID 41153298, 2025). "Patients in Group 2, the mitral atresia group, carried variants in genes related to mitral atresia, including EP300, NOTCH1, and TTN." (PMID 41153298, 2025).
Moyamoya disease (1 paper, 2022). Moyamoya disease (MMD) is a rare intracranial arteriopathy involving progressive stenosis of the cerebral vasculature located at the base of the brain causing transient ischemic attacks or strokes. "This study recognized TTN as a new familial gene marker for moyamoya disease and moreover, demonstrated that CRISPR-Cas12a has the advantages of rapid detection, low cost and simple operation, and has broad prospects in the practical application of rapid detection of MMD mutation sites." (PMID 35355511, 2022). "Our study identified TTN, a new specific candidate gene in familial moyamoya disease." (PMID 35355511, 2022).
multiminicore disease (1 paper, 2022). "For example, CNM has been associated with at least seven genes, including MTM1, DNM2, RYR1, TTN, BIN1, CCDC78 and SPEG, whereas RYR1 variations can cause central core disease (CCD), multiminicore disease (MmD), core-rod myopathy, CNM and CFTD." (PMID 35081925, 2022).
neuroblastoma (1 paper, 2025). Neuroblastoma (NB) is the most common solid, extracranial childhood tumor. "Other notable genes include (i) NPBF3, part of the neuroblastoma breakpoint family; (ii) APOL5, from the apolipoprotein L gene family; (iii) CHIA, which plays a role in chitin degradation; and (iv) TTN, which encodes a prominent protein in striated muscle." (PMID 39774017, 2025).
orofacial cleft (1 paper, 2022). A disorder of facial skeleton that is characterized by cleft lip and/or cleft palate that result in feeding, speech and hearing problems caused by failures during development. "The protein-truncating DNMs were found in ACTL6A, ARHGAP10, MINK1, TMEM5 and TTN genes, all of which are loci with substantial annotation, functional and/or animal model data supporting their roles in orofacial clefts." (PMID 35817949, 2022).
paraneoplastic syndrome of the nervous system (1 paper, 2019). "Anti-titin and anti-SOX1 often present with other classical paraneoplastic antibodies (anti-Hu, Ri, Yo etc.)in paraneoplastic syndrome of the nervous system." (PMID 31694559, 2019).
parasitemia (1 paper, 2017). "Some of the differentially abundant proteins such as SAA, CRP, Titin, Apo E exhibited gradual alterations in their serum abundances with an increase in parasitemia." (PMID 28667326, 2017).
paroxysmal tachycardia (1 paper, 2024). A form of tachycardia which begins and ends in an acute (or paroxysmal) manner. "The TTN gene was associated with both paroxysmal tachycardia and other arrhythmias." (PMID 38390584, 2024).
penile carcinoma (1 paper, 2021).
Pleural effusion (1 paper, 2023). The presence of an excessive amount of fluid in the pleural cavity. "For example, in case 2092 with skin oedema, pleural effusion, and talipes equinovarus, two pathogenic compound heterozygous variants in the TTN gene were identified." (PMID 37880672, 2023).
prostate adenocarcinoma (1 paper, 2023). "Although the exact roles of these genes in NEPC development remain to be elucidated, some of them (i.e., TTN, MUC16, and KMT2D) are reportedly associated with disease progression and treatment resistance in prostate adenocarcinoma and other types of cancers." (PMID 37025467, 2023).
pulmonary valve stenosis (1 paper, 2024). The pathologic narrowing of the orifice of the pulmonary valve. "The third echocardiography displayed an obvious increase in Peak Vel of TTN+/- mice, showing that pulmonary valve stenosis and pulmonary aortic stenosis may appear in 6-month-old TTN+/- mice." (PMID 38381767, 2024).
rectum adenocarcinoma (1 paper, 2025). An adenocarcinoma arising from the rectum. "This study investigates the impact of Titin (TTN) gene mutations on radiotherapy sensitivity in rectum adenocarcinoma (READ) by examining changes in the tumour immune microenvironment." (PMID 39748197, 2025).
renal cell carcinoma (1 paper, 2022). "The mutation rate of VHL in renal cell carcinoma was the highest, followed by PBRM1, TTN, and SETD2." (PMID 36186476, 2022).
Respiratory insufficiency (1 paper, 2012). "For example, our identification of a probable TTN mutation in a patient with myopathy with cytoplasmic aggregates and respiratory insufficiency widen the clinical spectrum compared to previous studies." (PMID 22526018, 2012).
rotator cuff tears (1 paper, 2022). "Because of the important role of TTN itself in muscle, the TTN-derived circRNAs are also more likely to be involved in muscle-related functions, which means further studies are needed to demonstrate the effect of these TTN-derived circRNAs in rotator cuff tears." (PMID 36111133, 2022).
sarcoidosis (1 paper, 2023). Sarcoidosis is a multisystemic disorder of unknown cause characterized by the formation of immune granulomas in involved organs. "Enriched genes including MPO (myeloperoxidase), CXCL11, IL1A, CXCL10, FCGR3B, IL1B, TTN (titin), BATF2, VIP (vasoactive intestinal peptide), TLR3, CCR2, TLR7, and CR1 wereclosely related to sarcoidosis." (PMID 38137330, 2023). "Biomarkers including TTN (titin) and STAT1 are widely involved in sarcoidosis." (PMID 38137330, 2023).
sarcoma (1 paper, 2020). A usually aggressive malignant neoplasm of the soft tissue or bone.
schwannoma (1 paper, 2025). A benign, usually encapsulated slow growing tumor composed of Schwann cells. "This independent observation in nervous system tumors suggests that TTN mutations may potentially affect the biological behavior of schwannomas through mechanisms such as influencing cellular mechanical stability, signaling, or as yet unknown functions in Schwann cells." (PMID 41209567, 2025).
sick sinus syndrome (1 paper, 2023). A constellation of signs and symptoms which may include syncope, fatigue, dizziness, and alternating periods of bradycardia and atrial tachycardia, which is caused by sinoatrial node dysfunction. "TTN interacts with other ion channel proteins, leading to sick sinus syndrome (SSS) when variations occur." (PMID 36721086, 2023).
Sinus bradycardia (1 paper, 2024). Bradycardia related to a mean resting sinus rate of less than 50 beats per minute. "Still, some gene mutations, such as NOTCH genes, ACTC1, MYH7, MYBPC3, TTN, and HCN4, among others, have been implicated with the HCN4 gene responsible for sinus bradycardia in some patients." (PMID 39677872, 2024).
skin cancer (1 paper, 2020). "In addition, the results from the database showed that TTN was highly expressed in skin cancer tissues compared with adjacent normal tissues." (PMID 32820147, 2020).
spastic cerebral palsy (1 paper, 2019). A form of cerebral palsy wherein spasticity is the exclusive impairment present. "This study was initiated to correlate hip adductor muscle changes intrinsic to the sarcomere—specifically, titin isoforms and sarcomere length—to the severity of hip displacement in children with spastic cerebral palsy." (PMID 31227002, 2019).
Syncope (1 paper, 2022). A transient loss of consciousness (i.e., characterized by a rapid onset, a short duration, and a spontaneous and complete recovery) due to cerebral hypoperfusion. "Two patients (3.7%) had pathogenic and likely pathogenic variants (PV/LPV) in cardiac syncope-related genes TTN and MYH7." (PMID 36005429, 2022).
systolic heart failure (1 paper, 2020). Heart failure caused by abnormal myocardial contraction during systole leading to defective cardiac emptying. "Patients with systolic heart failure have increased expression of the N2BA titin transcriptional variant that encodes a longer and softer titin protein, which correlates with decreased passive tension and increased left ventricular end diastolic volume." (PMID 32859027, 2020).
thyroid (1 paper, 2025). "Additionally, autoimmune thyroid disorders are characterized not only by thyroid-specific antigen targeting but also by a broader systemic immune activation, which may contribute to the generation of neuromuscular junction antibodies, including AChR-Ab and Titin-Ab." (PMID 41393996, 2025).
thyroid nodule (1 paper, 2025). A small circumscribed mass in the THYROID GLAND that can be of neoplastic growth or non-neoplastic abnormality. "In addition, TSHR, TTN, PIK3CA, and EIF1AX mutations in thyroid nodules categorized as indeterminate are uncommon and are typically verified as benign." (PMID 40586006, 2025).
thyroid tumor (1 paper, 2022). A benign or malignant neoplasm affecting the thyroid gland. "We aimed to evaluate the common mutated genes (JMJD1C, MALAT1, MUC16, PDZD2, PKHD1, RYR1, SLA and TTN) between thyroid tumor and normal samples." (PMID 35996174, 2022).
ventricular septal defect (1 paper, 2022). The presence of a defect (opening) in the septum that separates the two ventricles of the heart. "The large spectrum of observed cardiologic phenotypes suggests that titin‐mediated defects (caused by TTN mutations) could underlie certain cardiac conditions with or without skeletal muscle involvement, such as ventricular septal defect." (PMID 35819063, 2022).
cancer (170 papers, 2014 to 2026). A tumor composed of atypical neoplastic, often pleomorphic cells that invade other tissues. "Owing to the large size of the TTN gene, recurrent mutations are frequently observed across cancer datasets, but the clinical and biological significance of these alterations, particularly in the germline setting, remains incompletely understood." (PMID 41883887, 2026). "pySCENIC transcription factor analysis of single-cell transcriptomes revealed that NANOS1, a transcription factor, was significantly enriched in TTN-deficient cancer cells with high DLL4 expression." (PMID 41326912, 2025). "The study found a positive correlation between the number of mutations in the titin gene and the number of mutations in the cancer cells." (PMID 39944242, 2025). "MDSCs cocultured with TTN-deficient cancer cells transfected with a stable TTN-knockout plasmid increased glycolytic markers such MCT4, GLUT4, and LDHA." (PMID 41326912, 2025). "The TTN gene is known to acquire an abundance of somatic driver mutations strongly associated with several primary cancers." (PMID 39944242, 2025). "An study reported that mutations in the TTN gene indicate a high tumor mutation burden (TMB) state in 33 cancer types, including KIRC." (PMID 40854626, 2025). "MDSCs obtained from patients’ peripheral blood, co-cultured with primary cancer cells from patients with TTN mutation, secreted more lactic acid and tended to display pro-tumorigenic phenotypes." (PMID 41326912, 2025). "And the expression level of DLL4 was significantly suppressed in TTN-deficient cancer cells after NANOS1 knockdown." (PMID 41326912, 2025). "ANKRD1 localizes to the nucleus and is a component a complex called Titin that carries cancer-associated “driver” mutations." (PMID 38402174, 2024). "According to reports, TTN mutations are common in many types of cancer and are related to TMB status." (PMID 38571596, 2024). "TTN is one of the most commonly mutated genes in the pan-cancer cohort and is associated with poorer prognosis in a variety of human solid tumors." (PMID 37240946, 2023). "The TTN gene is susceptible to cancer protein kinase, encodes the major polypeptide expressed in oncogenesis, and is found in many functional cell types." (PMID 37239452, 2023). "TTN was considered to be the most frequently mutated gene in the pan-cancer cohort, with the highest correlation between the number of mutations and TMB." (PMID 38057871, 2023). "TTN is a commonly mutated gene in cancer and has a prominent role in predicting immune checkpoints and prognosis in solid tumours." (PMID 37730847, 2023). "Many scholars have reported that TTN gene mutation is related to the occurrence and development of various cancers, and the main type of TTN mutation is Multi_Hit." (PMID 37305390, 2023). "Recent studies have found that TTN is one of the most commonly mutated genes in various cancers, including metastatic TNBC." (PMID 35979353, 2022). "While MUC16 and TTN genes mutation were previously reported to correlate with prognosis, tumor mutation burden, and immunotherapy efficacy in cancers." (PMID 36685901, 2022). "Because of their generally very high mutation rates in most cancers, TTN alone or other FLAGS have been suggested as potential surrogates for TMB which is predictive in terms of responsiveness to immune checkpoint inhibitors." (PMID 36229065, 2022). "TTN, the gene considered to be most frequently mutated in the pan-cancer cohort, tended to have missense mutations in LIHC." (PMID 34603396, 2021).
cancer (continued). "we found that the immune signatures (CD8+ T cells, CD4+ T cell, Macrophage, Neutrophil and Dendritic cell) showed significantly higher enrichment levels in TTN-wildtype than in TTN- mutated cancers in LIHC (P < 0.01)." (PMID 33861762, 2021). "We evaluated the existence of any relationship between TTN mutation and immunostimulatory signature using 8145 pan-cancer data sets that contained both mutation and gene expression data for enrichment analysis." (PMID 32821429, 2020). "In their study, TTN was ranked as the single most prevalent gene among 518 protein kinase genes in 210 different human cancers associated with an extremely high density of cancer driver mutations." (PMID 32731431, 2020). "TTN was identified as the most frequently mutated gene within the pan-cancer cohort, and its mutation number best correlated with TMB assessed by WES (rho = 0.917, p < 2.2e-16)." (PMID 32821429, 2020). "The TTN encodes a structural protein, and although its biologic role in relation to cancer is still debatable, some studies have shown that the TTN gene is immunologically relevant." (PMID 32664247, 2020). "Titin (TTN) was also selected as a non-cancer gene because it has a high mutation prevalence probably due to its massive size." (PMID 26474971, 2015). "Our study offers fresh perspectives on the involvement of the TTN gene in cancer, indicating that TTN mutations may impact the radiotherapy sensitivity of READ cells." (PMID 39748197, 2025). "Thus, the TTN gene has been reported to be overexpressed, misexpressed, or mutated frequently in several cancers, including KIRC." (PMID 40854626, 2025). "Recent studies suggest that TTN mutations may influence cancer cell sensitivity to therapy through various mechanisms, including DNA repair and cell cycle regulation." (PMID 39748197, 2025). "In our study, we evaluated whether ghrelin, titin, and irisin can be a useful diagnostic marker, a prognostic marker of cancer development in these patients, and whether the levels of these proteins depend on the nutritional status of the patients." (PMID 38275878, 2024). "In addition, the biological function of TTN mutations in the development of cancer has been questioned, as TTN mutations have been strongly associated with cardiac and skeletal muscle diseases but rarely with oncological diseases." (PMID 37035196, 2023). "Importantly, this research was the first to construct a clinical prognostic model associated with TTN mutation, which can be used as a reference for other cancers that also have high TTN mutation rates." (PMID 36704353, 2022). "However, when these mutated reagents were tested on A1-MAGE-A3 (cancer) and A1-Titin (normal) positive cells we observed little difference in their abilities to trigger a T-cell response." (PMID 26758806, 2016). "However, considering the large size of the protein and prevalence of TTN mutations identified in other studies unrelated to cancer, it is presently hard to determine whether mutations in TTN act as drivers or are only passengers in NSCLC6." (PMID 25112956, 2014).